BCAR1 (BCAR1 scaffold protein, Cas family member)
Description:
Docking protein which plays a central coordinating role for tyrosine kinase-based signaling related to cell adhesion. Implicated in induction of cell migration and cell branching. Involved in the BCAR3-mediated inhibition of TGFB signaling (By similarity).
Synonyms: CAS; CASS1; CRKAS; P130Cas; CAS1
Tractability: Antibody: its Gene Ontology location is reachable by antibodies, with high confidence. PROTAC: ubiquitination databases record sites on it; its protein half-life has been measured.
Gene: Protein-coding gene on chromosome 16 (75,228,181 to 75,268,053, reverse strand). Ensembl gene ENSG00000050820.
Subcellular location: Cell junction, focal adhesion; Cytoplasm; Cell projection, axon
Subcellular location (Human Protein Atlas): Focal adhesion sites; Plasma membrane; Cytosol; Nucleoli; Nucleoli fibrillar center
Pathways (Reactome):
Signal Transduction: Downstream signal transduction; PTK6 Regulates RHO GTPases, RAS GTPase and MAP kinases; VEGFA-VEGFR2 Pathway; p130Cas linkage to MAPK signaling for integrins
Gene Ontology:
Molecular function: protein binding; protein kinase binding
Biological process: actin filament organization; antigen receptor-mediated signaling pathway; B cell receptor signaling pathway; cell chemotaxis; cell migration; cellular response to hepatocyte growth factor stimulus; endothelin receptor signaling pathway; hepatocyte growth factor receptor signaling pathway; integrin-mediated signaling pathway; positive regulation of cell migration; positive regulation of endothelial cell migration; vascular endothelial growth factor receptor signaling pathway; cell adhesion; cell division; cell surface receptor protein tyrosine kinase signaling pathway; epidermal growth factor receptor signaling pathway; G protein-coupled receptor signaling pathway; insulin receptor signaling pathway; neurotrophin TRK receptor signaling pathway; platelet-derived growth factor receptor signaling pathway; regulation of apoptotic process; regulation of cell growth; T cell receptor signaling pathway
Cellular component: cytoplasm; focal adhesion; plasma membrane; ruffle; cytosol; protein complex involved in cell adhesion; axon
Genetic constraint (gnomAD): Loss-of-function variants: 33 observed, 56.72 expected, observed/expected ratio (o/e) 0.58, 90% interval 0.44 to 0.78. The synonymous counts are far from expectation, so gnomAD's model fits this gene poorly and the ratio says little. Missense variants: 1,313 observed, 1,118.1 expected, observed/expected ratio (o/e) 1.17, 90% interval 1.12 to 1.23. Synonymous variants: 626 observed, 509.1 expected, observed/expected ratio (o/e) 1.23, 90% interval 1.15 to 1.31.
Homologues: Orthologues: chimpanzee BCAR1 (99% identical), macaque BCAR1 (97% identical), dog BCAR1 (92% identical), rabbit BCAR1 (92% identical), pig BCAR1 (91% identical), rat Bcar1 (91% identical), guinea pig BCAR1 (91% identical), mouse Bcar1 (91% identical), tropical clawed frog bcar1 (59% identical), zebrafish bcar1 (57% identical), Drosophila melanogaster p130CAS (25% identical). Paralogues in human: NEDD9 (39% identical), CASS4 (23% identical), EFS (21% identical).
Diseases named in the same sentence as BCAR1 in open-access papers:
BCAR1 is named in the same sentence as 75 diseases in open-access papers, as found by Europe PMC text mining. Sharing a sentence is not in itself a finding about the gene and the disease. The quoted sentences say what the papers report.
breast carcinoma (82 papers, 2005 to 2026). "p130Cas/BCAR1 (Breast Cancer Anti-Estrogen Resistance 1) is an adaptor protein of the Crk-associated substrate (Cas) family." (PMID 39036012, 2024). "The CRK adaptors are also linked to breast cancer anti-estrogen resistance proteins BCAR1 and BCAR3, which also associate with each other." (PMID 37686522, 2023). "Initially, various studies about BCAR1 was mostly focus on the association with breast cancer and lung cancer." (PMID 36263425, 2022). "This is of special interest as BCAR1 was initially identified as overexpressed in breast cancer, where it was associated with poor outcome and therapy resistance." (PMID 34830244, 2021). "Knowledge on BCAR1/p130Cas function and clinical association is mainly based on studies in mammary carcinomas." (PMID 34830244, 2021). "In analogous studies on p130Cas/BCAR1 in breast cancer cells, mutation of all 15 of its SD YxxP tyrosines to phenylalanine resulted in reduced proliferation, migration and invasion." (PMID 29876004, 2018). "A positive correlation between the expression of BCAR1/p130Cas and ErbB2 has been found in human breast cancers and the co-expression of these two genes is associated with shorter overall survival and a higher risk of developing distant metastasis." (PMID 25606587, 2014). "Increased CAS/BCAR1 levels in breast cancer patients are associated with premature disease recurrence, decreased response to tamoxifen treatment, and lower survival rate." (PMID 23974298, 2014). "In spite of this, in patients with primary breast cancer, high BCAR1/p130Cas levels are associated with poor relapse-free survival and poor overall survival." (PMID 25606587, 2014). "In fact, in the aggressive A17 mouse mammary tumour cells, p130Cas/BCAR1 silencing induces loss of mesenchymal features and acquirement of epithelial-like traits, including the re-expression of the cell-cell adhesion molecule E-cadherin." (PMID 25606587, 2014). "In ER+ breast cancers, p130Cas is associated with disease progression and resistance to tamoxifen; hence, the alternative name of breast cancer anti-estrogen resistance 1 (BCAR1)." (PMID 22948112, 2012). "High BCAR1 expression is linked to poor prognosis in breast cancer patients, while upregulation of NEDD9 contributes to the metastatic behavior of melanoma and glioblastoma cells." (PMID 21765937, 2011). "AND-34/BCAR3 (Breast Cancer Anti-Estrogen Resistance 3) associates with the focal adhesion adaptor protein, p130CAS/BCAR1." (PMID 19365570, 2009). "Because BCAR1 protein levels have been associated with clinical outcome for breast cancer patients, further studies are needed to resolve the underlying mechanism." (PMID 15642172, 2005). "By considering that BCAR1 encodes breast cancer anti-estrogen resistance 1, we hypothesized that the enrichment of the BCAR1 PPI subnetwork might differ in patients with cancers." (PMID 36737517, 2023). "Consequently, BCAR1 has been shown to be overexpressed in diverse malignancies, including cancers of the breast, lung, liver and brain, and has been linked to adverse features in these entities." (PMID 29304771, 2018). "Furthermore, increased levels of the human ortholog of CAS, BCAR1, are associated with exacerbated prognosis in breast cancer patients." (PMID 28808245, 2017). "The mechanisms underlying the up-regulation of p130Cas/BCAR1 and Nedd9 in breast cancer are still largely unknown." (PMID 25606587, 2014). "Moreover, overexpression of BCAR1 causes tamoxifen resistance in tamoxifen-sensitive breast carcinoma cells." (PMID 19680458, 2010). "Moreover, studies of human breast cancer specimens have shown that high BCAR1 expression is associated with poor prognosis and also predicts a poor response of recurrent disease to treatment with tamoxifen." (PMID 15642172, 2005). "p130Cas, also known as breast cancer anti-estrogen resistance 1 (BCAR1), is an adaptor protein that interacts with several proteins at the focal adhesion intracellular part." (PMID 41596231, 2026).
breast carcinoma (continued). "Meanwhile, another research has highlighted the positive regulatory role of breast cancer anti-estrogen resistance protein 1 (BCAR1) in LSEC fenestrae." (PMID 39741334, 2024). "Pirin also interacts with breast cancer anti-estrogen resistance 1 (BCAR1) protein that activates RAC1." (PMID 38033031, 2023). "It has been shown that there is a relationship between BCAR3 expression and the regulation of breast cancer cell migration through a change in the location of BCAR1 in the cytoplasmic membrane." (PMID 35453754, 2022). "Upon performing the STITCH/STRING analysis, we observed that zyxin interacts with BCAR1 (Breast cancer anti-estrogen resistance protein 1), which coordinates tyrosine kinase-based signaling." (PMID 33808029, 2021). "The T allele was predicted to disrupt the interaction between bta-miR-1291 with its putative target genes, increasing the protein levels of TCEA2 (transcription elongation factor A) and BCAR1 (breast cancer anti-estrogen resistance 1)." (PMID 33419037, 2021). "The transcriptional control of p130Cas/BCAR1 in human breast cancer cells is partly due to the transcription factor EGR1 and its coregulator NAB2." (PMID 34708040, 2021). "How is BCAR1/p130Cas transcriptionally regulated and which are the mechanisms responsible for its overexpression In breast cancer?" (PMID 34708040, 2021). "The same report also identifies breast cancer anti-estrogen resistance protein 1 (BCAR1) to be a substrate of BRK, where in vivo knockdown of BRK disrupts phosphorylation of BCAR1 tyrosine residue 165, preventing its activation." (PMID 33391524, 2021). "BCAR1/p130Cas drives treatment resistance in breast cancer and other malignancies, but EREG expression is associated with suitable outcomes, especially in left-sided mCRC." (PMID 34830244, 2021). "BCAR1 is overexpressed in a variety of malignancies, e.g., cancers of the breast, lung, liver, and brain." (PMID 34326687, 2021). "The protein that had the highest numbers of the functional connections to the cellular movement was breast cancer anti-estrogen resistance 1 (BCAR1)." (PMID 33144694, 2021). "BCAR1 expression is high in a variety of cells and cell lines, including endothelial cells from veins and skin, breast cancer cells, and LUAD cells." (PMID 34326687, 2021). "Since p130Cas is induced by anti-estrogen therapy and doxorubicin in breast cancer cells, the effects of standard CRC chemotherapy on p130Cas/BCAR1 and EREG expression were investigated in CRC cell lines and metastasis tissues samples." (PMID 34830244, 2021). "High expression of BCAR1 can alter breast epithelial cell morphology, which can lead to tumor formation as well as cell growth, invasion, and metastasis of breast cancer cells." (PMID 33001583, 2020). "Breast cancer anti-estrogen resistance 1 (BCAR1/p130Cas) is a scaffold protein that serves as a hub in cellular signaling." (PMID 29304771, 2018). "FAs have also been reported to exhibit degradative activity resulting from recruitment of MT1-MMP via p130Cas/BCAR1 (Breast cancer anti-estrogen resistant) in a complex with FAK." (PMID 29876004, 2018). "Breast cancer anti-estrogen resistance 1 (BCAR1/p130cas) is a hub for diverse oncogenic signaling cascades and promotes tumor development and progression." (PMID 29304771, 2018). "In breast cancer models the expression of the Cas family scaffold members NEDD9 (HEF1, Cas-L) or p130Cas (BCAR1) promotes phenotypes associated with epithelial-to-mesenchymal transition (EMT) in a Src kinase-dependent manner." (PMID 29464017, 2018). "The breast cancer anti-estrogen resistance protein 1 (BCAR1) is involved in B cell receptor signaling pathway." (PMID 26538867, 2015).
breast carcinoma (continued). "Seven over-expressed breast cancer genes, namely BCAR1, HSD17B1, MMP14, PLAU, SFRP2, SPP1 and VCAN, had increased promoter methylation and their promoters contained the tumor-specific hypermethylated A-6 or A-7 HMRs." (PMID 25706888, 2015). "The contribution of p130Cas/BCAR1 and Nedd9 to specific oncogenic pathways in different breast cancer subtypes is described in detail in the paragraphs below." (PMID 25606587, 2014). "Although there is a clear correlation between the emergence of tamoxifen resistance in breast cancer and the association of BCAR3 with p130Cas/BCAR1, the available data on the functional meaning of this interaction appear controversial." (PMID 25606587, 2014). "The relevance of the adaptor proteins p130Cas/BCAR1 and Nedd9 in breast cancer has been highlighted by numerous in vivo and in vitro studies." (PMID 25606587, 2014). "p130Cas/BCAR1 cooperates with ErbB2 not only in mammary cell transformation but also in driving breast cancer cell migration and invasion and formation of metastasis." (PMID 25606587, 2014). "Conversely, the LOX pro-peptide (LOX-PP), which is released during the maturation of the pro-LOX enzyme, reduces breast cancer cell motility by attenuating phosphorylation and activation of p130Cas/BCAR1." (PMID 25606587, 2014). "The ability of p130Cas/BCAR1 to control the remodelling of the actin cytoskeleton represents a mechanism commonly used to induce migration of breast cancer cells." (PMID 25606587, 2014). "Phosphoproteomic data from human breast cancer cell lines have revealed that basal cancer cells exhibit higher tyrosine phosphorylation of p130Cas/BCAR1 compared with luminal cancer cells, despite similar p130Cas/BCAR1 expression in the two subgroups." (PMID 25606587, 2014). "The link between p130Cas/BCAR1 and epithelial-mesenchymal transition is supported by the role of p130Cas/BCAR1 in the control of breast cancer cell plasticity." (PMID 25606587, 2014). "In this review, we summarize and discuss the most recent findings regarding the role of p130Cas/BCAR1 and Nedd9 in the normal mammary epithelium and in different breast cancer subtypes." (PMID 25606587, 2014). "Further in vivo analyses have shown that in the MMTV-NeuT mouse model of ErbB2 tumourigenesis, over-expression of p130Cas/BCAR1 accelerates the onset of mammary tumours, which are characterized at the molecular level by increased activation of c-Src and Akt." (PMID 25606587, 2014). "We used breast carcinoma MCF7 cells to overexpress or siRNA-deplete BCAR1 and NEDD9, individually or in combination, and monitored total expression of E-cadherin and its partner proteins α-, β-, and p120catenin." (PMID 21765937, 2011). "Interest in this protein has focused on the ability of BCAR3 (Breast Cancer Anti-Estrogen Resistance 3), the human homolog of AND-34, to induce anti-estrogen resistance in breast cancer in concert with p130Cas (BCAR1)." (PMID 19365570, 2009). "In clinical specimens, BCAR1 was found to be an independent marker (multivariate analyses also including ERα) for early recurrence of breast cancer and for failure of tamoxifen treatment of recurrent disease." (PMID 15642172, 2005). "It has been shown that p130Cas/BCAR1 levels of expression impact on breast cancer cells EMT." (PMID 34708040, 2021). "Eventually, the results of mechanism analysis suggested that BCAR1 might promote the metastasis of breast cancer by facilitating Rap 1 signaling pathway." (PMID 34055638, 2021). "In addition, AKT (Protein kinase B (PKB) signaling pathway downstream targets, e.g., Breast Cancer Anti-estrogen Resistance 1 (Bcar1) and Provirus integrating site Moloney murine leukemia virus 3 (Pim3), were also differentially regulated." (PMID 34884498, 2021). "The gene encoding p130Cas was identified by screening estrogen receptor-positive human breast cancer cells as responsible for promoting tamoxifen resistance and for this reason named BCAR1 (Breast Cancer Antiestrogen Resistance 1)." (PMID 34708040, 2021).
breast carcinoma (continued). "For example, the interaction of Zyxin with NOLC1 (Nucleolar and coiled-body phosphoprotein 1) and BCAR1 (Breast cancer anti-estrogen resistance protein 1) suggest a novel role of zyxin in ribosomal processing and in tyrosine kinase-based signaling, respectively." (PMID 33808029, 2021). "Additionally, STAT3, FAK, and BCAR1 are relevant PTK6 substrates in breast cancer, and PTK6 protects breast cancer cells from autophagic cell death induced by loss of anchorage, suggesting that PTK6 can inhibit autophagic processes." (PMID 33109128, 2020). "Indeed, high levels of p130Cas/BCAR1 in T47D breast cancer cells promote the assembly of a multi-protein complex including ERα, c-Src, and PI3K." (PMID 25606587, 2014). "The role of p130Cas/BCAR1 as a mediator of ErbB2 signalling was initially demonstrated in breast cancer cell lines devoid of ErbB receptors, in which over-expression of ErbB2 was sufficient to induce cell migration by triggering the coupling between p130Cas/BCAR1 and Crk." (PMID 25606587, 2014). "Furthermore, there are notable similarities between this network and that present in human basal and claudin-low breast cancer cell lines, including increased tyrosine phosphorylation of Met, Cav1, Bcar1 and Tln1." (PMID 25200860, 2014). "Additional mechanisms that implicate p130Cas/BCAR1 in breast cancer invasion have been described." (PMID 25606587, 2014). "Together, these observations indicate that p130Cas/BCAR1 up-regulation might be a priming event in the development of basal-like breast cancer." (PMID 25606587, 2014). "In parallel, in MCF-7 breast cancer cells, exposure to the selective ER modulator tamoxifen has been found to induce Src-mediated phosphorylation of p130Cas/BCAR1, which in turn promotes the activation of a pro-survival signalling pathway involving FAK and Akt." (PMID 25606587, 2014). "In MCF-7 mammary tumour cells, up-regulation of Nedd9 results in enhanced AurA activity leading to centrosomal and mitotic spindle abnormalities, whilst a weaker effect can be seen after changes of p130Cas/BCAR1 expression." (PMID 25606587, 2014). "Over the past decade, p130Cas/BCAR1 and Nedd9 have emerged as key players in the control of many different aspects of mammary gland biology, including mammary epithelial cell homeostasis and mammary tumour cell behaviour." (PMID 25606587, 2014). "Initially, intensive studies were focused on the correlation between breast cancer and BCAR1." (PMID 22558353, 2012). "BCAR1 overexpression also correlates with poor prognosis in breast cancer patients." (PMID 21765937, 2011). "This confirms our hypothesis that TNK2 can operate separately from BCAR1 to facilitate migration and invasion of breast cancer cells." (PMID 18435854, 2008). "Our data suggest that TNK2 can enhance migration and invasion of breast cancer cells via preservation of EGFR expression, notwithstanding its previously reported signalling via BCAR1, explaining its oncogenic behaviour in vitro and correlation with metastatic human breast cancer in vivo." (PMID 18435854, 2008). "Finally, combined with the KEGG signaling pathways, it could be speculated that the BCAR1 could affect the occurrence and metastasis of breast cancer by regulating the Rap 1 signaling pathway." (PMID 34055638, 2021). "The results suggested that metastasis associated RNAs, including AHRR, TTC34, CNTRL, ANKRD52, BCAR1, TMEM151B, PANX2, hsa-miR-105-5p, hsa-miR-4435, hsa-miR-5691, hsa-miR-92a-1-5p, and LINC01742 could serve as the prognostic biomarkers of breast cancer patients." (PMID 34055638, 2021). "Notably, up-regulation of BCAR1 can alter the morphology of breast epithelial cell resulting in that the occurrence and development of breast cancer, which is exactly consistent with our result that the expression of BCAR1 was clearly upregulated in M1 patients compared with M0 samples." (PMID 34055638, 2021).